CXCL11 (C-X-C motif chemokine ligand 11)
Diseases named in the same sentence as CXCL11 in open-access papers (continued):
Sharing a sentence is not in itself a finding about the gene and the disease.
cancer (continued). "For example, we found that the TME induced the transformation of CXCL11+ macrophages with the manifestation of M1-like macrophages into SPP1+ macrophages with a higher M2 signature, promoting cancer progression." (PMID 36357424, 2022). "Out of the detected hub genes, six (CCL20, CXCL1, CXCL3, CXCL8, CXCL11, and MMP1) were among over-expressed vDEGs which have been corroborated by the GEPIA in both COAD and READ cancer types." (PMID 35333898, 2022). "For example, CXCL9, CXLC10, and CXCL11/CXCR3 has two main functions: it activates the immune response through the paracrine pathway and promotes the proliferation and metastasis of cancer cells through the autocrine pathway." (PMID 35992864, 2022). "CXCL10, CXCL9, CXCL11/CXCR3 is an important axis for immune activation, which is necessary for developing novel cancer therapy." (PMID 36685901, 2022). "CXCL9, CXCL10, CXCL11, CXC12, CXCL13, and CXCL14 expression in the tissue adjacent to carcinoma was significantly different." (PMID 35181719, 2022). "While CXCL11-Ig based therapy inhibited inflammatory autoimmunity within the central nervous system, administration of CXCL10-Ig suppressed cancer." (PMID 34944943, 2021). "For the multivariate Cox model for cancer-specific survival, CXCL9 showed significant results and CXCL11 showed a trend toward significance as independent prognosticators after controlling for the same covariates." (PMID 34501934, 2021). "In agreement with the present findings, BRG1 was found to promote TXNIP, CXCL11 and IL6 expression in GBM cancer stem cells, suggesting a broad role of these genes in the pro‐tumorigenic role of BRG1 in GBM." (PMID 33528916, 2021). "CXCL11 stimulation upregulated circUBAP2 expression, which was significantly higher in HCC tissues than para-carcinoma tissues." (PMID 33707417, 2021). "CAFs secreted significantly higher levels of CXCL11 than normal fibroblasts (NFs), and CXCL11 also had comparatively higher expressions in HCC tissues, particularly in metastatic tissues, than para-carcinoma tissues." (PMID 33707417, 2021). "CXCR3 has been identified as a crucial receptor for NK chemotaxis in response to cancer-secreted ligands, CXCL9, CXCL10, and CXCL11." (PMID 32546200, 2020). "AIRE stimulates the expression of the cancer-related proinflammatory genes MMP9, CXCL10, and CXCL11." (PMID 32012175, 2020). "Known and predicted targets of miR-125b reported in prior studies of cancers characterized by BRAF alterations include MLK3, KLF13, CXCL11, and FOXA1." (PMID 30131528, 2018). "The IFN-γ/CXCL9, CXCL-10, CXCL-11/CXCR3 axis can be a double-edged sword in cancer, promoting an anti-tumor effect but also increasing the capability of cancer cell proliferation, angiogenesis and metastasis." (PMID 30631766, 2018). "Among them, CXCL10, CXCL11 and CCL11 are chemokines that direct cell migration in development, immunity, inflammation and cancer." (PMID 28938587, 2017). "Detailed researches on the functions of CXCL12‐CXCR4/CXCR7 pathways and their cross‐talks with CXCR3, CXCL11, CXCL10, and CXCL9 remain urgently warranted, which help lead to safer and more efficient use of their molecular inhibitors in targeted cancer therapy." (PMID 28544785, 2017). "Pan-cancer analysis of the relationship between OBSCN expression and chemokines revealed a significant negative correlation between OBSCN expression and a variety of chemokines, including CXCL10, CXCL11, CCL11, CCL21, and CCL23." (PMID 40149008, 2025). "Furthermore, IFN-γ regulates the expression and secretion of CXCL9, CXCL10, and CXCL11, along with their cognate receptor CXCR3 in various immune cells such as T cells, NK cells, monocytes, DCs, and cancer cells." (PMID 40040705, 2025). "CXCL11 is among the protein members of the CXC chemokine family, and its induction through interferon (IFN) suggests its functional involvement in the evolution of various cancers." (PMID 39820173, 2025).
cancer (continued). "In particular, chemokines, including CXCL8, CXCL10, CXCL11, CXCL16, CCL26, and CCL7, as well as chemokine receptors, including CXCR3, CCR2, CCR5, and CCR1, were positively correlated with MRPL13 expression in various cancer types." (PMID 37827692, 2023). "CXCL11 expression was significantly higher in tumoral tissue than in nontumoral tissue for most types of cancer." (PMID 35935945, 2022). "Then we checked the relationship between CXCL11 expression and immune-related genes, including chemokine receptors, other chemokines, immunostimulatory genes, immunosuppressive genes, and MHC genes, across all 33 cancers." (PMID 35935945, 2022). "Moreover, in cancer-induced bone pain, inhibition of CXCL10, CXCL11 and CXCL13 enhanced morphine analgesic properties in rats." (PMID 36618360, 2022). "Apart from that, recent studies have also revealed that the diverse functions of C-X-C Motif Chemokine Ligand 11 (CXCL11) included restraining angiogenesis, disrupting the proliferation of different cell types, playing a role in cancer invasion, and upregulating adhesion properties." (PMID 36091786, 2022). "On the contrary, CXCL11 expression was remarkably upregulated in rectal adenocarcinoma, but was not correlated with a better prognosis in cancer patients." (PMID 35702353, 2022). "It suggests that SAA1, CXCL10, CCR5, CCL19, CXCL11, CXCL13, and CCL5 have important function in immunotherapy for cancer patients, and may be used as key regulator genes of immunotherapy." (PMID 34093667, 2021). "The transcripts included in the final signature were BCL10, CXCL11, CYBB and GBP1 and, based on their expression levels, our algorithm was able to classify plasma samples into cancer and control with a receiver operating characteristic (ROC) area under the curve (AUC) of 0.92 to 0.95." (PMID 33580122, 2021). "We thus explored CXCL11 expression and ICB‐related gene signatures across cancer types." (PMID 34047476, 2021). "Also, the transcriptional expressions of CXCLs family members were correlated with patients' individual cancer stages and nodal metastasis status, especially for CXCL2, CXCL3, CXCL4, CXCL7, CXCL9, CXCL10, CXCL11, and CXCL12." (PMID 32963527, 2020). "Additionally, however, we noted a specific set of genes encoding chemokines and cytokines, namely CCL4, CCL8, CXCL10, CXCL11, IFI44L, IDO1, and IFNG that were upregulated in 9p CNG cancers." (PMID 29212506, 2017). "Cytokine stimulation of carcinoma samples, but not of normal tissue, resulted in a significant increase of CXCL11 production (p=0.0455)." (PMID 29163806, 2017). "Additionally, an analysis of COAD and adjacent non-cancerous tissue samples from the TCGA database confirmed significant increases in CXCL1, CXCL8, CXCL9, and CXCL11 in cancer tissues, while CCL22 showed no significant change." (PMID 38791448, 2024). "Additionally, the level of CXCL11 was closely correlated with prognosis, TMB, MSI, immune checkpoints, TME, immune cell infiltration, and immune-related genes, providing insights to the role of CXCL11 in various cancer types." (PMID 35935945, 2022). "CXCL10 and CXCL11 are ligands of chemokine CXCR3, which can regulate the migration, differentiation and activation of immune cells, and are related to the selective migration and linear development of CD4 + and CD8 + T cells, thereby affecting the therapeutic effect of cancer." (PMID 35087563, 2021). "CXCL9, CXCL10, and CXCL11 (C-X-C motif chemokine ligand 9, 10, and 11, respectively) are chemokines that share functions as ligands of CCR3, stimulating antitumoral immunity, but they can also promote proliferation and metastasis in cancer cells in an autocrine pathway, as recently reviewed." (PMID 32117120, 2020). "Using cancer-related pathway probes, we showed that STAT3 inhibited the expression of several IFN response genes in GICs, such as the chemokines CXCL9, CXCL10 and CXCL11, which is consistent with the finding that STAT3 can inhibit the expression of IFN response genes." (PMID 29774125, 2018).
cancer (continued). "Correlation analyses revealed a significant correlation between plasma CXCL11 levels and PD-L1 expression on non-classical monocytes, which corroborates earlier studies that have shown the involvement of CXCL11 in the regulation of checkpoint molecule PD-L1 in human cancers." (PMID 38609887, 2024). "Among them, interferon (IFN) inducible CXC chemokine, CXCL9 (Mig), CXCL10 (IP-10) and CXCL11 (I-TAC), are multifunctional chemokine orchestrating immunity and angiogenesis via shared G-protein coupled receptor CXCR3, thus, these ligands might play a crucial role in cancer." (PMID 26910919, 2016). "Consistently, the protein level of CXCL11 was increased in the nonmetastatic HCC tissue samples and the metastatic HCC tissue samples compared with the in para-carcinoma tissues, and was further increased in the metastatic HCC tissue samples compared with the nonmetastatic HCC tissue samples." (PMID 33707417, 2021). "Compared to uninfected cancers, the infected cancers had significant upregulation of nine cellular factors (FCER2, MS4A1 (CD20), PLUNC, TNFSF9, TRAF1, CXCL11, IFITM1, PPARG, and FCRL3), implying that EBV is not an innocent bystander with respect to biochemical impact." (PMID 22929309, 2012). "Besides, the CXCL11 mRNA levels were increased in the nonmetastatic HCC tissue samples and metastatic HCC tissue samples compared with the para-carcinoma tissue samples and were greater in the metastatic HCC tissue samples than in the nonmetastatic HCC tissue samples." (PMID 33707417, 2021).
cardiovascular disease (6 papers, 2015 to 2023). "Interestingly, CCL5, CXCL10, and CXCL11 — which have been reported to play a key role in the pathogenesis of cardiovascular disease — appeared to be most upregulated (more than 10-fold)." (PMID 26837541, 2016). "Our investigation of CXCL11 levels in the serum of ATAA patients did not reveal a significant induction of its expression compared to the control group (p = 0.2481) or the group of patients with cardiovascular disease (p = 0.1474)." (PMID 37238945, 2023).
immune disorders (4 papers, 2022 to 2025). "Besides, CXCL10, CXCL11, and IL-10 also played critical roles in immune disease." (PMID 40458609, 2025). "Particularly, CXCL9, CXCL10, and CXCL11 in cluster 7 were closely associated with disease progression and immune disorders, irrespective of whether the patients had been treated with ART." (PMID 36408648, 2023). "In particular, the SH2B3 locus on chromosome 12 stands out in this regard, with GWAS signals for seven immune disorders colocalizing with three trans-regulated proteins (THPO, ICAM2, CXCL11), all involved in positive regulation of immune system processes (GO:0002684)." (PMID 35078996, 2022). "Some IRPs in cluster 7, such as CXCL11, CXCL9, TNF, CXCL10, and IL18, are closely associated with HIV-1 disease progression and immune disorders, irrespective of whether patients received ART treatment." (PMID 36408648, 2023).
infectious disease (4 papers, 2015 to 2022). A disorder directly resulting from the presence and activity of a microbial, viral, or parasitic agent in humans. "On chromosome BTA6, the CXCL11 gene was identified and has been associated with immune response during pathological processes, including inflammation and autoimmune and infectious diseases in different cattle populations." (PMID 35886015, 2022). "CXCL11 and its receptor, CXCR3, are likely to be associated with important inflammatory diseases of livestock, as well as with protective immunity to infectious diseases and tumors." (PMID 27098998, 2016).
neurological diseases (3 papers, 2022 to 2025). "Ligands of the CXCR3 receptor include CXCL9, CXCL10, and CXCL11, exhibit varied roles across different neurological disorders." (PMID 40781073, 2025).
heart disease (2 papers, 2020 to 2022). "Interestingly, TgGRK5 cardiomyocytes also showed dysregulated expression of several immune-related genes, including Cxcl11, Cxcl13, and Il-15, that have been previously associated to leukocyte migration and to cardiac dysfunction and remodeling during heart disease." (PMID 33560342, 2022). "Interestingly, C-X-C Motif Chemokine Ligand 10 (Cxcl10), and CxCl11 proteins were both upregulated in patients with heart disease and some studies indicate this is true for DOX cardiotoxicity as well." (PMID 32960902, 2020).
inflammation (2 papers, 2020 to 2025). Aberrant reaction of the microcirculation characterized by movement of fluid and leukocytes from the blood into extravascular tissues. "CXCL11 is a chemokine that attracts CXCR3+ T cells and is implicated in synovial inflammation in RA." (PMID 40606440, 2025). "Furthermore, the inactivation of NF-κB reportedly inhibits C-X-C motif chemokine ligand 11 (CXCL11) expression in retinal pigment epithelial cells and CXCL11 is also associated with microbial stimuli to intestinal inflammation." (PMID 32527308, 2020).
respiratory diseases (2 papers, 2023 to 2025). "In multiple animal models of respiratory diseases, the treatment with XC221GI led to controlling the levels of CXCL9, CXCL10, CXCL11, IL-6 and IL-8, and to decrease of extent of the pathogen-driven cytokine storm." (PMID 37214455, 2023).
adenocarcinoma (1 paper, 2020). A common cancer characterized by the presence of malignant glandular cells. "In agreement with studies carried out in adenocarcinoma cell lines, we found similar upregulation of genes such as IDO1, GBP1, CXCL9, CXCL10, and CXCL11 in response to IFN-γ, all of which are also known to be upregulated in IBD patients." (PMID 33396621, 2020).
central nervous system diseases (1 paper, 2022). "Two of them are Cxcl9 and Cxcl11, which are involved in Th1-type response, correlating with T-cell infiltration; the comprehension of CXCR3 (C-X-C Motif Chemokine Receptor 3)/CXCL9′s binding mechanism of action is considered crucial for the treatment of central nervous system diseases." (PMID 35806178, 2022).
heart (1 paper, 2024). "Antibodies to the chemokine CXCL11 have been associated with chronic heart, lung, and renal allograft dysfunction." (PMID 39408890, 2024).
kidney disease (1 paper, 2025). "CXCL11 is a proinflammatory chemokine implicated in kidney disease induced by interferon signaling." (PMID 40485680, 2025).
psychiatric disorder (1 paper, 2024). A disorder characterized by behavioral and/or psychological abnormalities, often accompanied by physical symptoms. "CXCR7 is a G-protein-coupled receptor and can interact with either CXCL11 or CXCL12 that has been implicated in various aspects of inflammation and psychiatric disorders." (PMID 38674048, 2024).
CXCL11 also shares sentences with these, for which no sentence is quoted: bacterial infection (6 papers); Graves disease (4); Sepsis (4); liver (3); serous ovarian cancer (3); Addison’s disease (2); allergic reactions (2); esophageal cancer (2); fibrosis (2); head and neck squamous cell carcinoma (2); incontinentia pigmenti (2); Insulin resistance (2); interstitial lung disease (2); latent infection (2); lupus nephritis (2); myocarditis (2); neuropathic pain (2); pancreatic adenocarcinoma (2); post-traumatic stress disorder (2); alcoholics (1); allergic rhinitis (1); Allergy (1); alveolitis (1); Alzheimer disease (1); Angina (1); angiosarcoma (1); Atrophy (1); autoimmune Addison’s disease (1); biliary cirrhosis (1); bipolar disorder (1).
A further 78 diseases each share a sentence with CXCL11 in 1 paper.